IL6 (interleukin 6)
Diseases named in the same sentence as IL6 in open-access papers (continued):
Sharing a sentence is not in itself a finding about the gene and the disease.
diabetes (continued). "Inflammation affects insulin signalling and increases beta-cell death, and markers of inflammation, such as elevated interleukin 6 (IL-6) and C-reactive protein (CRP) levels, have been found to be associated with future diabetes risk." (PMID 23843750, 2013). "Type 2 diabetes mellitus and insulin resistance (IR) are characterized by the release of pro-inflammatory cytokines, such as TNFα and IL-6, resulting in an inflammatory state." (PMID 23166628, 2012). "High levels of IL-6 in diabetes stimulate fibrinogen synthesis by the hepatocytes, representing a link between inflammation and the prothrombotic state." (PMID 22347666, 2012). "The use of anti-IL-6 blockers as an anti-inflammatory therapeutic in diabetes has therefore been debated." (PMID 23087692, 2012). "Diabetes significantly increases the degree of inflammation and the release of IL-6 in DN group compared with the normal control group (P < 0.05)." (PMID 22991571, 2012). "Circulating oxidized LDL-containing immune complexes (oxLDL-IC) are increased in diabetes stimulate synthesis of IgGs in addition to other proinflammatory cytokines such as IL-1β, IL-6, IL-18, and TNF-α in Mono Mac 6 cells and primary human macrophages." (PMID 23267348, 2012). "IL-6 is also an important inflammatory mediator in diabetes and increased levels correlate with IR, although it appears to have a dual role." (PMID 23087692, 2012). "Mixed effects models were performed for CRP, IL-6, and IP-10, adjusting for the following covariates: access type, coronary artery disease, sex, age, race, HD initiation, diabetes mellitus, infection, access thrombosis, and number of days after access surgery." (PMID 22121485, 2012). "Interleukin-1 beta (IL-1β), interleukin 6 (IL-6), and C-reactive protein (CRP) are three inflammatory markers which have been shown to predict the development of diabetes, although this association is interpreted controversially." (PMID 23251619, 2012). "For the serum biomarkers, subjects with incident diabetes had lower levels of adiponectin (P = 0.001), but higher levels of hsCRP (P<0.001), IL-6 (P = 0.014), TNF-α R2 (P<0.001) and A-FABP (P<0.001)." (PMID 22615828, 2012). "Interleukin-1β is a key regulator of inflammation both in T1DM and T2DM and has been shown to induce pancreatic β-cell apoptosis and exacerbate the systemic inflammation associated with diabetes, for instance by augmenting adipocyte TNF-α and IL-6 production." (PMID 23087692, 2012). "The role of inflammation in diabetes is becoming more evident and elevated circulating interleukin (IL)-1β, IL-6, and C-reactive protein (CRP) are predictive of T2DM." (PMID 23087692, 2012). "Elisa analysis demonstrated that diabetes increased the levels of left ventricular IL-6, IL-1α and tumor necrosis factor-α (TNF-α) as compared with the non-diabetic group." (PMID 22432030, 2012). "IL-6 was increasing with increasing systolic pressure both in the patients with MS and in the healthy volunteers (r = 0.354, p = 0.047), while smoking and diabetes were positively correlated with IL-6 only in the patients' group." (PMID 22558213, 2012). "It is possible that increased TNF-alpha and IL-1beta levels affect the expression of IL-6, considering that we detected an increase in the number of immunostained cells to IL-6 after 9 and 12 months of diabetes induction." (PMID 22611374, 2012). "IL-6 was increasing with increasing systolic pressure both in the patients with MS and in the healthy volunteers, while smoking and diabetes were positively correlated with IL-6 only in the patients' group." (PMID 22558213, 2012). "Exclusion of individuals with diabetes resulted in attenuated effect estimates for IL-6, VEGF, and TNF-α, suggesting that some of the effects were attributable to individuals with diabetes." (PMID 22336131, 2012).
diabetes (continued). "Diabetes resulted in a noticeable increase in IL-6 (26.5 ± 6.3 vs 17.1 ± 4.7 pg/mg protein, P < 0.05) and TNF-α (89.7 ± 10.2 vs 55.9 ± 9.5 pg/mg protein, P < 0.05) compared with the control group." (PMID 21232147, 2011). "RMD also inhibited diabetes-induced elevation in the levels of interleukin (IL)-1β, IL-6, interferon-γ and tumor necrosis factor-α." (PMID 21716679, 2011). "Receiver operating characteristic (ROC) analysis for each clinical and cytokine parameter revealed interleukin-6>interleukin-8>diabetes mellitus>Murray's LISS as the best outcome predictors." (PMID 21991318, 2011). "Future studies need to explore this potential further, particularly as IL-6 is attracting increasing interest in the diabetes and CVD arenas." (PMID 21818333, 2011). "In the present study, the left ventricles from diabetic rat hearts showed a significant up-regulation of IL-6, MEK5 and ERK5, suggesting that activated IL-6/MEK5/ERK5 signaling cascade participate in the diabetes-induced pathologic hypertrophy." (PMID 21792366, 2011). "The cytokine levels of TNF-α, IL-1β, and IL-6 were increased in the patients with diabetes and diabetic rats." (PMID 21716679, 2011). "Our findings also suggest potential associations of elevated circulating IL-6, a measure known to predict CVD and diabetes, with biological ageing, observations which require further study to tease out potential mechanistic links." (PMID 21818333, 2011). "In wt mice, diabetes resulted in a clear increase in TNFα, IL-6 and IL-1β mRNA expression levels (p<0.01, p<0.01 and p<0.05, respectively) and in a tendency to higher IFNγ and caspase-1 mRNA levels (n.s.)." (PMID 20856927, 2010). "In comparison to controls, the diabetes only (DM+LF−) group had high levels of IL-6 and GM-CSF, which was significant (p<0.01)." (PMID 20559443, 2010). "In the retinas of diabetic wt mice, we also found significantly increased levels of TNFα, IL-6 and IL-1β mRNA expression and a tendency to increased IFNγ and caspase-1 mRNA, indicating some degree of local inflammation after 8 weeks of diabetes." (PMID 20856927, 2010). "BMI and albumin decreased with increasing age, while waist-hip ratio, systolic blood pressure, prevalence of diabetes, adiponectin, IL-6, and bilirubin increased with age." (PMID 21170382, 2010). "The effect of diabetes on the expression of various inflammatory (TNFα, IL-6, IL-1β and IFNγ) and apoptosis markers (caspase-1) was also evaluated in intact retinas from wt, ApoE−/−, TNFα−/− and ApoE−/−/TNFα−/− mice." (PMID 20856927, 2010). "In PRP pre-treated group, both VEGF and IL-6 was correlated with ΔFT only, while in control group, VEGF was statistically correlated with duration of diabetes and strongly with grade of retinopathy and IL-6 was strongly correlated with HbA1c." (PMID 23675018, 2007). "From this study, it was clearly showed that PRP accelerated the diabetic macular thickening and increased vitreous level of IL-6, indicating that IL-6 plays critical role of PRP induced macular edema." (PMID 23675018, 2007). "Persistence ofsignificant difference between the cases with IDDM monitored for along time and controls in terms of IL-1β, IL-2, IL-6, andTNF-α supports continuous activation during the latestages of diabetes." (PMID 16864906, 2006). "In all stages of diabetes higher levels of IL-1β andTNF-α and lower levels of IL-2 and IL-6 were detected." (PMID 16864906, 2006). "Nanoflowers demonstrate rapid wound healing due to reduced inflammation, tissue regeneration, and angiogenesis in the diabetes-induced wound model by modulating tumor necrosis factor-α, CD-44, Ki-67, collagen deposition, ROS, interleukin-1β (IL-1β), IL-8, and IL-6 expression." (PMID 41737838, 2026).
diabetes (continued). "Across diabetes, myocardial infarction, heart failure, and neuroinflammatory states, shared pathways (e.g., IL-6/STAT3, TGF-β/SMAD, PI3K/AKT, MAPK/ERK, oxidative stress) suppress neuronal excitability, promote neuron-glia-fibroblast coupling, and culminate in neurofibrotic remodeling." (PMID 41684000, 2026). "Understanding the interplay between adiponectin, leptin, CRP, and IL-6 in this unique demographic may yield important insights into the pathogenesis of lean diabetes." (PMID 41523554, 2025). "Higher IL-6 levels have a significant predictive value for incident diabetes." (PMID 40606939, 2025). "Hyperglycemia and dyslipidemia result in the elevated circulating levels of proinflammatory cytokines, such as tumor necrosis factor alpha (TNF-α), interleukin-6 (IL-6), interleukin-1β (IL-1β), and C-reactive protein (CRP) which, in turn, increase the risk of diabetes and vascular complications." (PMID 40004134, 2025). "Circulating interleukin-6 (IL-6) levels are often elevated in type 2 diabetes mellitus (T2DM)." (PMID 40141782, 2025). "In a study by Xia Li, it was found that IL-6, IL-8, hypercholesterolemia, diabetes mellitus, and high-sensitivity C-reactive protein (hs-CRP) were independent predictors of restenosis risk in CAD patients who underwent percutaneous coronary intervention with drug-eluting stents." (PMID 39859253, 2025). "Therefore, we investigated the expression of proinflammatory cytokines Tnf-α and Il-6 in enlarged wounds on cutaneous wound healing in individuals with diabetes." (PMID 39921745, 2025). "Elevated IL6 and TNF levels have been observed in patients with type 2 diabetes, and these cytokines are linked to disease progression through pathways such as AGE-RAGE signaling pathways associated with diabetes complications." (PMID 40699728, 2025). "In addition, TNFR1 mediated 14.9% of the inverse association between diabetes and naïve CD4T cells independently of IL-6, while IL-6 mediated 3.6% of the association independently of TNFR1." (PMID 41280118, 2025). "Notably, the PI3K-Akt signaling pathway, a critical pathway in diabetes, was enriched with additional key targets, including IL6, HSP90AA1, FN1, MAPK1, AKT1, PIK3R1, and MAPK3." (PMID 40170727, 2025). "However, the aqueous preparation notably reduced the levels of IL-6, a cytokine upregulated in diabetes and known to trigger endothelial dysfunction, which can lead to atherosclerosis." (PMID 41155632, 2025). "Therefore, we investigated the expression of proinflammatory cytokines Tnf-α and Il-6 in cutaneous wound healing with diabetes." (PMID 39921745, 2025). "Additionally, the aqueous extract suppressed interleukin-6 (IL-6), a pro-inflammatory cytokine commonly elevated in diabetes." (PMID 41155632, 2025). "TNF-α, IL-1β, IL-6, NF-κB and IL-17A are multifunctional cytokines, that are mainly related to immune regulation, and play a crucial role in the occurrence and progression of diabetes." (PMID 40046742, 2025). "In addition, obese individuals expressed higher visceral levels of IL‐6 protein compared with normal‐weight controls, which has a more significant correlation with diabetes than total body fat." (PMID 39764565, 2025). "Macrophages, which play a crucial role in initiating immune responses by phagocytosing TB bacteria and secreting key cytokines such as TNF-α and IL-6, demonstrate impaired functionality in individuals with diabetes due to the presence of chronic, low-grade inflammation." (PMID 40917351, 2025). "Aging and diabetes are associated with elevated systemic levels of IL-1β, TNF-α, and IL-6." (PMID 41155632, 2025). "The presence of TNF-α, IL-6, and IL-12 mRNA could suggest early chronic inflammation in the vascular systems of individuals with diabetes, indicating the potential development of further diabetic complications." (PMID 40298831, 2025). "Therefore, we investigated the expression of proinflammatory cytokines Tnf-α and Il-6 in enlarged wounds on cutaneous wound healing in diabetes." (PMID 39921745, 2025).
diabetes (continued). "Despite the statistical significance of the observed associations, the mediating role of IL-6 does not explain the totality of the diabetes-related effect." (PMID 40606939, 2025). "Clarifying how IL-6 relates to metabolic control in diabetes, particularly in T1D, may help identify patients at higher inflammatory risk and guide its use as a biomarker of disease burden." (PMID 41010714, 2025). "Increased plasma levels of IL-6 were demonstrated in Chinese diabetes patients with neuropathy." (PMID 40002826, 2025). "In experimental diabetes, IL-6 shows some beneficial effects." (PMID 40002826, 2025). "Patients with IL-8 serum concentrations ≥ 40.26 pg/mL had higher systolic and diastolic blood pressure before dialysis; more history of hypertension, diabetes, coronary artery disease, and heart failure; and higher serum concentrations of IL-6, IAA, TGFβ, and lower PTH." (PMID 41003499, 2025). "The abnormal elevation of pro-inflammatory cytokines (such as TNF-α, IL-1βand IL-6) may exacerbate islet dysfunction in individuals with diabetes." (PMID 41300029, 2025). "Moreover, systemic metabolic disturbances - particularly type 2 diabetes mellitus, elevated serum LDL-C concentrations and heightened IL-6 levels were identified as independent predisposing factors for CMVO development." (PMID 40988197, 2025). "The pathophysiology of diabetes and cardiovascular disease has been linked to chronic low-grade inflammation, which is characterized by elevated levels of inflammatory markers like C-reactive protein (CRP) and interleukin-6 (IL-6)." (PMID 38846218, 2024). "Therefore, the fat tissue constitutes a large source of circulating IL-6 in patients with diabetes and metabolic syndrome independently on the kidney involvement." (PMID 39723211, 2024). "In diabetes, plasma mtDNA was moderate positive correlation with IL-6." (PMID 38241222, 2024). "Other studies have shown that in STZ diabetes, there is an increase in pulmonary infiltration with neutrophils and macrophages and an increase in the secretion of proinflammatory cytokines (IL-1β, IL-6)." (PMID 38792932, 2024). "Given IL-6’s role in diabetes pathophysiology, more research into its molecular mechanisms could lead to novel approaches for preventing T2DM complications." (PMID 39857603, 2024). "Biomarkers such as IL-6 and IL-8could provide constant insight into inflammation and disease status in time, making saliva collection especially helpful forlongitudinal analysis of chronic conditions like diabetes and periodontal disease." (PMID 40230914, 2024). "Consequently, targeting IL-6 or its downstream signaling cascades emerges as a promising therapeutic strategy for effectively managing diabetes mellitus, with particular emphasis on T2D." (PMID 38667300, 2024). "Diabetes is an inflammatory disease, and elevated blood glucose level and insulin insensitivity leads to the activation of immune cells, thereby secreting interleukins and cytokines such as IL-6 and TNF-α and aggravating the inflammatory response." (PMID 39144694, 2024). "Therefore, cancer patients had significantly lower levels of adiponectin, IL6, and a lower A/L ratio compared to control patients after adjustment for BMI, diabetes, and parity." (PMID 38339282, 2024). "Low-grade inflammation and elevated cytokines, particularly interleukin 6, may accompany hyperfibrinogenemia in diabetes mellitus." (PMID 39184698, 2024). "Moreover, YME1L overexpression led to reduced mRNA abundance of common SASP markers, including Tgf-β, Il-6, IL-1α, and Tnf-α, compared with control mice with diabetes." (PMID 38494498, 2024). "Based on the results obtained from this study, we propose that measuring the serum IL-6: omentin-1 ratio in patients with type 2 diabetes mellitus may assist in identifying the early stages of diabetic nephropathy before the onset of microalbuminuria." (PMID 39131026, 2024).
diabetes (continued). "In addition, certain inflammatory biomarkers, including adiponectin, CRP, and interleukin 6 (IL-6), have been correlated with the transition from a prediabetic state to diabetes." (PMID 39839274, 2024). "Among the clinical variables, IL6 had positive correlations with age (r=0.221, P=0.018), duration of diabetes (r=0.212, P=0.024), Cys C (r=0.299, P=0.002), and AST/ALT (r=0.314, P<0.001) and significant negative correlations with eGFR (r=−0.337, P<0.001) and 25(OH)D (r=−0.22, P=0.023)." (PMID 39525855, 2024). "Moreover, Amini and colleagues, demonstrated how tropisetron’s down-regulation of TNF-α and IL-6 levels had an anti-inflammatory effect on diabetes-induced liver abnormalities." (PMID 38629089, 2024). "Furthermore, IL-6 has been shown to directly impair pancreatic beta cells, thereby contributing to the pathogenesis and progression of diabetes." (PMID 39707185, 2024). "These associations (with exception of HDL2-apoA-I and CETP activity) remained significant after adjustment for age, sex, BMI, smoking status, presence of diabetes, total cholesterol, creatinine level, interleukin-6 (IL-6), albumin, systolic and diastolic blood pressure, and NT-proBNP." (PMID 39244794, 2024). "In G2, the induction of diabetes significantly (at P = 0.05) increased in serum glucose, glycated proteins, renal indices, interleukin-6 (IL-6), K+, immunoglobulins, and lipid peroxidation, while decreased Ca++, Na+, and other antioxidants in the kidney tissue homogenate." (PMID 38577302, 2024). "In addition, we did not observe any elevation in cytokines associated with both an immune response and the development of diabetes (IL-1β, IL-6, IL-8, and TNFα) using ddPCR." (PMID 38400070, 2024). "The increased secretion of IL-6 is also known to be a response to increased TNF levels and both TNF and IL-6 have been shown to be present in higher concentrations in children with diabetes or risk factors for diabetes." (PMID 38396488, 2024). "Interleukin-6 is a pleiotropic cytokine with a dual role in diabetes and oxidative stress." (PMID 39857603, 2024). "Comorbidities such as diabetes and hypertension, although accounted for, may have influenced IL-6 levels, making it difficult to isolate the effects of RA on systemic inflammation." (PMID 39469275, 2024). "Therefore, the objective of the study was to estimate serum omentin-1 and IL-6 levels in type 2 diabetes mellitus (T2DM) with early stages of nephropathy." (PMID 39131026, 2024). "In people with concurrent diabetes, the existence of hyperglycemia and hyperlipidemia may have a direct effect on IL-6 trans-signaling, which may enhance the severity of NAFLD." (PMID 38535313, 2024). "Based on the results obtained from this study, we propose that measuring the serum interleukin-6: omentin-1 ratio in patients with type 2 diabetes mellitus may assist in identifying the early stages of diabetic nephropathy before the onset of microalbuminuria." (PMID 39131026, 2024). "The proposed mechanism involves the elevation of serum glucagon-like peptide-1 (GLP-1) levels, which subsequently reduce serum interleukin-6 (IL-6) levels and downregulate IL-6 expression in white adipose tissue, serving as an inflammatory marker in mice with diabetes." (PMID 39014451, 2024). "Finally, research has shown that inflammation contributes to the onset of diabetes, and physical activity raises interleukin-6(IL-6) levels, which combat inflammation, thus indirectly regulating glycemic irregularities." (PMID 39185125, 2024). "Balancing IL6's regenerative capabilities against its inflammatory actions will be key in developing a therapeutic strategy that is both effective and safe for patients with diabetes." (PMID 38270651, 2024). "Therefore, it is not surprising that VEGF-A from both macrophages and fibroblasts was reduced in diabetes, and the improvement of diabetic wound healing by macrophage-expression of IL6 also improved angiogenesis through VEGF-A." (PMID 38270651, 2024).